MSLN (mesothelin)
Diseases named in the same sentence as MSLN in open-access papers (continued):
Sharing a sentence is not in itself a finding about the gene and the disease.
mesothelioma (continued). "One of the characteristics of mesothelin is its limited expression in healthy organs and overexpression in mesotheliomas." (PMID 39315086, 2024). "The engrafted tumor retained key mesothelioma features, including strong positivity for Pancytokeratin, Calretinin, and WT1, as well as typical expression patterns for mesothelioma Mesothelin and EMA." (PMID 39768223, 2024). "A vast majority of these trials include patients with mesothelioma, ovarian and pancreatic cancer, where mesothelin expression has been well characterised." (PMID 39548594, 2024). "We evaluated mesothelin’s expression in non-mesothelioma tumor tissues to further assess its potential value as a diagnostic biomarker." (PMID 39315086, 2024). "Preclinical studies have investigated several targets for use in mesothelioma including mesothelin (MSLN), FAP, cMET, and pan-ERbB." (PMID 39409190, 2024). "Mesothelin is a cell surface glycoprotein expressed in pancreatic, ovarian, mesothelioma cells, and squamous epithelium." (PMID 38667465, 2024). "Our prior studies have shown that hYP218 CAR T cells, targeting the cell membrane‐proximal epitope of mesothelin, demonstrate significant anti‐tumour efficacy in preclinical models of mesothelioma, ovarian and pancreatic cancers." (PMID 39548594, 2024). "The predicted amino acid sequence of the canine mesothelin was compared with that of the human mesothelin after confirming mesothelin expression in the canine mesothelioma via RT-PCR." (PMID 39315086, 2024). "RT-PCR was performed using total RNA extracted from primary mesothelioma cultures to confirm mesothelin gene expression in dogs." (PMID 39315086, 2024). "Both preclinical and clinical studies examining MSLN expression in mesothelioma, pancreatic cancer, and lung adenocarcinoma show evidence that enhanced MSLN expression portends a reduction in survival in animals and humans." (PMID 39174744, 2024). "Mesothelin, a glycoprotein with a role in cell adhesion and which is overexpressed in mesothelioma, can be detected in the blood." (PMID 39409190, 2024). "Mesothelin (MSLN) has been identified as a target antigen for CAR T cell treatment of mesothelioma, lung, ovarian, and other cancers because of its high expression on tumor cells and limited expression on mesothelial cells." (PMID 39576012, 2024). "In humans, mesothelin is normally expressed at low levels on the mesothelial cell surface and is overexpressed in numerous cancers, including mesothelioma." (PMID 39315086, 2024). "In vitro, anti-mesothelin TRuC T cells have demonstrated effective cytotoxicity against different cancer cell lines with high mesothelin expression including mesothelioma, NSCLC, and ovarian adenocarcinoma tumor cells." (PMID 38610930, 2024). "Leveraging the cross-reactivity of JZQ-B4 variants to mouse MSLN, we assessed the efficacy and toxicity of CAR affinity variants utilizing a subcutaneous mesothelioma tumor model with MSTO-211H/hMSLN cells." (PMID 39576012, 2024). "Herein, mesothelin gene expression in canine mesothelioma was first assessed via conventional RT-PCR, followed by sequence analysis of cultured canine pericardial mesothelioma cells." (PMID 39315086, 2024). "Mesothelin is a cell-surface glycoprotein that is overexpressed in several tumor types including mesothelioma, as well as ovarian and pancreatic adenocarcinoma." (PMID 38610930, 2024). "In our examples, tumor-selective mRNAs in the HNCs (EGFR, CDH1) were stable, however, mesothelioma-selective mRNAs (i.e., mesothelin and WT1) were reduced." (PMID 38744944, 2024). "Other potential targets include mesothelin (MSLN), a glycophosphatidylinositol (GPI)-linked cell surface protein, that is highly expressed on the surface of mesothelial cells, mesothelioma, and epithelial ovarian cancer cells." (PMID 38919533, 2024). "After confirming mesothelin expression, we assessed its levels in major organ tissues and compared them with those in the mesothelioma tissues using quantitative PCR (qPCR)." (PMID 39315086, 2024).
mesothelioma (continued). "To conclude, in this Australian cohort the percentage of MSLN‐expressing mesothelioma tissues and the distribution of MSLN were lower than reported elsewhere." (PMID 37040900, 2023). "Mesothelin is a cell membrane glycoprotein that is expressed in mesothelioma, lung adenocarcinoma, pancreatic adenocarcinoma, colorectal adenocarcinoma, serous ovarian cancer, gastric adenocarcinoma, and breast cancer." (PMID 37631232, 2023). "First, MSLN‐staining would be advised to select patients for anti‐MSLN targeted therapies in mesothelioma." (PMID 37040900, 2023). "Mesothelin indicates the strongest promising antigen candidate in mesothelioma malignancies due to its upregulation and apparent correlation with tumor activity." (PMID 37469419, 2023). "Thirty‐two of 67 (48%) mesothelioma patient samples stained positive for MSLN using a threshold for positivity of immunostaining in ≥ 5% of tumour cells, a threshold reported previously." (PMID 37040900, 2023). "This study aimed to assess the intensity and distribution of MSLN immunostaining in mesothelioma, and to determine the prognostic value of MSLN expression by histochemical‐score (H‐score)." (PMID 37040900, 2023). "The PE24 moiety was utilized in SS1-Fab-DS3-PE24 IT, targeting mesothelin expressed by pancreatic carcinoma, mesothelioma gastric, and lung carcinomas." (PMID 36808279, 2023). "Although MSLN is overexpressed in mesothelioma, our cohort demonstrates inter‐patient heterogeneity in MSLN expression." (PMID 37040900, 2023). "Overall, 39 of 67 (58%) of mesothelioma tissues stained positive for MSLN at any level of expression." (PMID 37040900, 2023). "For calretinin and mesothelin, the appropriate interval to detect mesothelioma is about one year prior to the clinical diagnosis." (PMID 38136442, 2023). "scRNA-Seq acquired from untreated MESO patients with pleural effusion and biopsy tumor tissues demonstrated that these nine EMT genes were overexpressed predominantly in mesothelioma cells characterized by MSLN expression." (PMID 36901697, 2023). "Calretinin and mesothelin were the first biomarkers in combination to be validated for the early detection of mesothelioma using liquid biopsies." (PMID 38136442, 2023). "The cellular membrane biomarker mesothelin, which is primarily expressed in mesothelioma, has also been the subject of investigations." (PMID 37469419, 2023). "Previous clinical studies have attempted to inhibit invasion in mesothelioma patients by targeting mesothelin, a membrane-bound protein that stimulates anchorage-independent growth, migration, and invasion." (PMID 37146029, 2023). "To date, mesothelin is the only tumor biomarker to receive US FDA approval for clinical use in mesothelioma." (PMID 38053658, 2023). "Recently, He and colleagues demonstrated that MSLN control tumorigenicity and metastatic potential through epithelial-to-mesenchymal transition and stem properties of mesothelioma cell lines." (PMID 37901248, 2023). "The MN1 anti‐MSLN antibody was used to stain a formalin‐fixed paraffin‐embedded tissue microarray of histologically confirmed mesothelioma from 75 consecutive patients who had undergone pleurectomy with or without decortication." (PMID 37040900, 2023). "The combination of calretinin and mesothelin was validated for the early detection of mesothelioma approximately one year prior to the common diagnosis based on clinical symptoms." (PMID 38136442, 2023). "This rationale has guided the development of targeted immunotherapies against mesothelin, a well-known biomarker expressed on the surface of mesothelioma cells." (PMID 36303838, 2022). "Encouragingly, when this cleaned and expanded GFP+ mCherry-negative library population was stimulated with H-226 target cells, a human mesothelioma cell line expressing high levels of MSLN, selective NFAT activation was already evident for ~ 1% of the cells." (PMID 35064152, 2022).
mesothelioma (continued). "Evaluating mesothelioma, an anti-MSLN Ab, [89Zr]Zr-amatuximab, detected MSLN-expressing xenografts, which can play a part in the patient selection for anti-MSLN targeted therapy." (PMID 35836956, 2022). "Mesothelin (MSLN) is a differentiation antigen mainly expressed on CAMs, OC cells and mesothelioma cells." (PMID 36268019, 2022). "The overall prognosis analysis of MSLN gene in mesothelioma showed that the higher the MSLN expression level, the longer the patient’s survival time and the better the prognosis." (PMID 36140611, 2022). "Mesothelin (MSLN) is a cell-surface antigen associated with tumor invasion, which is strongly expressed in many solid tumor types, including mesothelioma, lung cancer, breast cancer, and pancreatic cancer." (PMID 36497465, 2022). "RG7787-conjugated MSLN is being evaluated in phase I clinical trials on patients with MSLN-positive malignancies, including mesothelioma and ovarian, pancreatic, gastric, and triple-negative breast cancer (TNBC)." (PMID 36158673, 2022). "A meta-analysis reported a sensitivity of 32% for serum mesothelin with 95% specificity which makes it a weak biomarker for mesothelioma detection and a problematic biomarker of efficacy." (PMID 35987988, 2022). "To date, soluble mesothelin is the only tumor biomarker to receive US Food and Drug Administration approval for clinical use in mesothelioma, and it is under evaluation also as therapeutic target." (PMID 35328227, 2022). "To this end, we chose to target mature human mesothelin (hMSLN, AA residues 296-606) as a therapeutically relevant cell surface antigen highly expressed in several aggressive solid tumours including mesothelioma and pancreatic adenocarcinomas." (PMID 35064152, 2022). "Clinical trials of ERC/mesothelin-targeting agents have confirmed their safety and utility in mesothelioma and ovarian and pancreatic cancers." (PMID 35565327, 2022). "MSLN is a cell surface glycoprotein and tumor differentiation antigen expressed in some malignancies, such as mesothelioma." (PMID 35453596, 2022). "The combination of calretinin and mesothelin was additionally shown to be feasible for the early detection of mesothelioma using plasma samples of mesothelioma patients up to 15 months prior to MPM diagnosis." (PMID 36240245, 2022). "The overall prognosis analysis of MSLN gene in mesothelioma, the Log-rank test results showed a significant difference in survival time between high and low MSLN gene expression groups (p = 0.011)." (PMID 36140611, 2022). "This review summarizes the clinical studies that have examined mesothelin as a biomarker and therapeutic target in mesothelioma and explores future perspectives in its role to improve patient management." (PMID 34439085, 2021). "MSLN is expressed on the membrane of mesothelial cells of the peritoneal and pleural cavities, and overexpression of MSLN has been observed in mesothelioma, ovarian, lung, oesophageal, endometrial and breast cancers." (PMID 34359776, 2021). "Strengthened by these findings, anetumab ravtansine was investigated versus vinorelbine as second-line treatment for advanced mesothelioma with high-mesothelin expression, after failure of first-line platinum/pemetrexed chemotherapy." (PMID 33509252, 2021). "The first-in-human study evaluated anetumab ravtansine in patients with advanced solid tumors, enriched for cancer with known mesothelin overexpression (mesothelioma, ovarian and peritoneal cancer)." (PMID 33509252, 2021). "PF mesothelin has been studied as an alternative biomarker, as mesothelin is shed from mesothelioma tumour cells directly into pleural effusion fluid." (PMID 34209209, 2021).
mesothelioma (continued). "Since its discovery, mesothelin, a cell surface protein, has been a promising biomarker and therapeutic target due to its overexpression in mesothelioma and limited expression in normal cells." (PMID 34439085, 2021). "Tumor-differentiation antigen or mesothelin, derived from tumor proteins, are overexpressed in ovarian, pancreatic, and lung cancers, as well as mesothelioma." (PMID 34361141, 2021). "Mesothelin (MSLN) is a cell surface adhesion molecule which is overexpressed in 20–90% of cancer entities such as mesothelioma, triple negative breast, ovarian, lung, and pancreatic cancers." (PMID 34943898, 2021). "Inhibition of MSLN in mesothelioma cell lines has been shown to restore cell sensitivity after exposure to cisplatin." (PMID 32517181, 2020). "Immunotherapy strategies targeting MSLN are under investigation in various tumor subsets, such as mesothelioma and lung and breast cancer." (PMID 35582441, 2020). "The potential of calretinin and mesothelin to discriminate between mesothelioma cases and asbestos-exposed controls has been confirmed in various studies and recently, both markers have also been validated for the early detection of malignant mesothelioma." (PMID 32435497, 2020). "We performed studies using the overexpression or knockdown of ERC/mesothelin in mesothelioma cells to examine its effect on cellular morphology, growth kinetics, or migration/invasion activity, in vitro." (PMID 32677949, 2020). "Mesothelin is expressed in normal mesothelial cells and overexpressed in mesothelioma, lung, ovarian, and pancreatic cancer." (PMID 33273991, 2020). "Up to date, only the combination of the proteins calretinin and mesothelin has been validated for the early detection of mesothelioma using plasma samples taken up to 15 months before the clinical diagnosis." (PMID 32435497, 2020). "To date, no report exists that discusses the functional relationship between the ERC/mesothelin expression and histological differentiation in mesothelioma." (PMID 32677949, 2020). "Although mesothelin has been proposed as a marker for the diagnosis of mesothelioma, biomarker testing is recommended only for patients with a suspicious cytology who are not fit to undergo more invasive diagnostic testing." (PMID 33273991, 2020). "MSLN overexpression has been discovered in different tumors, including pancreatic cancer, in which almost 85% of cells express this protein, and of course up to 90% of mesothelioma cells are positive for MSLN." (PMID 35582441, 2020). "MSLN is a 40-kDa membrane-anchored glycoprotein that is frequently overexpressed in cancer types including mesothelioma, ovarian, lung, and pancreatic cancer." (PMID 30850485, 2019). "Mesothelin (MSLN) is a 40-kDa membrane protein that has been reported to be expressed on normal mesothelial tissue and highly expressed in mesothelioma and lung, pancreas, breast, ovarian, and gastric cancer." (PMID 30777106, 2019). "PM cells, referred as PM27 in the present work, express mesothelin, vimentin and keratin 5, considered as typical markers of mesothelioma." (PMID 30651596, 2019). "MSLN is a validated cancer target known to be overexpressed in mesothelioma, ovarian, lung, breast, and pancreatic cancer, with low expression in normal tissue." (PMID 30850485, 2019). "Mesothelin targeting CAR-T has been reported in mesothelioma, lung cancer, breast cancer, and pancreas cancer." (PMID 30777106, 2019). "Mesothelin, a glycoprotein normally expressed in mesothelial cells, is highly expressed in several cancers including ovarian, pancreatic, and mesotheliomas." (PMID 30134520, 2018). "LMB-100 is a recombinant immunotoxin, currently in phase I clinical trials that targets mesothelin (MSLN) a cell surface protein highly expressed in mesothelioma and lung adenocarcinoma." (PMID 30400835, 2018). "Up to 80% of patients with mesothelioma have high mesothelin expression and thus are candidates for anti-mesothelin immunotoxin therapy." (PMID 30441807, 2018).
mesothelioma (continued). "Another key step would be the combined evaluation of sCD157 and mesothelin in an attempt to improve diagnostics for all types of mesothelioma." (PMID 29854315, 2018). "We investigated the effect of shed antigen mesothelin on the tumor uptake of amatuximab, a therapeutic anti-mesothelin mAb clinically tested in mesothelioma patients." (PMID 29720923, 2018). "MSLN, a 40kDa glycoprotein that is overexpressed in many cancers including ovarian and mesotheliomas is suggested to play a role in cell survival, proliferation, tumor progression, and adherence." (PMID 30134520, 2018). "Firstly, RNA sequencing and western blot data obtained from the mesothelioma cell lines used to generate the lysate preparation validated mesothelin mRNA and protein expression." (PMID 30245692, 2018). "The AE17M mesothelioma tumor model is uniquely suitable to support clinical development of anti-mesothelin immunotoxins." (PMID 30441807, 2018). "To study the role of MSLN in lung cancer and mesothelioma, we first evaluated the expression level of MSLN in human cancer patients and cell lines." (PMID 28288645, 2017). "Knockdown of MSLN led to mesenchymal to epithelial transition and less aggressive behavior of lung carcinoma and mesothelioma cells." (PMID 28288645, 2017). "A recent meta-analysis on serum mesothelin showed that the sensitivity and the specificity were 61 and 87%, respectively, when compared with various non-mesothelioma diseases." (PMID 28335760, 2017). "We investigated in the present study to compare mesothelin, a well-established biomarker for mesothelioma, with midkine, a possible novel marker, in the diagnosis and the prognosis of malignant pleural mesothelioma." (PMID 28335760, 2017). "MSLN knockdown (shMSLN) and control (shC) mesothelioma cells were injected into NSG mice subcutaneously, and tumor formation and metastasis were determined." (PMID 28288645, 2017). "Consistent with previous studies, our presented results indicate an upregulation of MSLN in human lung tumor tissues and in lung carcinoma and mesothelioma cell lines." (PMID 28288645, 2017). "There is not currently a reliable blood-based biomarker available as for diagnosis and prognosis of mesothelioma except serum mesothelin." (PMID 28335760, 2017). "An initial study about mesothelin reported that an elevated serum concentration was indicative of mesothelioma with a sensitivity of 84% and a specificity of 100% in comparison with other pleural diseases and non-mesothelioma malignancy." (PMID 28335760, 2017). "We then investigated possible prognostic values of serum mesothelin and midkine in patients with mesothelioma." (PMID 28335760, 2017). "Two previous meta-analyses, for example, reported that both mesothelin and osteopontin showed 61 and 57% for the sensitivity and 87 and 81% for the specificity to differential diagnose mesothelioma from others, respectively." (PMID 28335760, 2017). "Mesothelin (MSLN), a plasma membrane differentiation antigen, is expressed at a high level in many human solid tumors, including 70% of lung cancer and nearly all mesotheliomas." (PMID 28288645, 2017). "Other studies however reported contradictory results that an elevated mesothelin level was a poor prognostic factor in mesothelioma." (PMID 28335760, 2017). "Nevertheless, the AUC of combined serum mesothelin and midkine to distinguish mesothelioma patients from benign asbestos pleurisy patients was significantly higher than that of midkine (p = 0.0329)." (PMID 28335760, 2017). "Multivariable Cox hazards regression analysis revealed diffuse membranous mesothelin expression in mesothelioma tumor cells to be a favorable prognostic factor (HR, 0.36; 95% CI, 0.21–0.64; P < 0.001)." (PMID 28460459, 2017). "In this study, we demonstrated that mesothelin levels in mesothelioma were greater than other pleural diseases when the serum concentrations was compared with respective diseases or the combination of all the diseases." (PMID 28335760, 2017).